PLSCR2 (phospholipid scramblase 2)
Description:
May catalyze calcium-induced ATP-independent rapid bidirectional and non-specific movement of phospholipids (lipid scrambling or lipid flip-flop) between the inner and outer leaflet of the plasma membrane. [Isoform 1]: Has no phospholipid scramblase activity, due to the lack of a N-terminal proline-rich domain.
Tractability: Antibody: UniProt predicts a signal peptide or a membrane-spanning region; its Gene Ontology location is reachable by antibodies, with medium confidence. PROTAC: ubiquitination databases record sites on it.
Gene: Protein-coding gene on chromosome 3 (146,391,421 to 146,495,991, reverse strand). Ensembl gene ENSG00000163746.
Subcellular location: Membrane; Nucleus (Isoform 1)
Subcellular location (Human Protein Atlas): Nucleoplasm; Endoplasmic reticulum; Vesicles
Gene Ontology:
Molecular function: protein binding; calcium ion binding; phospholipid scramblase activity
Biological process: phosphatidylserine exposure on apoptotic cell surface; plasma membrane phospholipid scrambling; positive regulation of innate immune response
Cellular component: nucleoplasm; nucleus; membrane; plasma membrane
Genetic constraint (gnomAD): Loss-of-function variants: 5 observed, 8.29 expected, observed/expected ratio (o/e) 0.6, 90% interval 0.31 to 1.26. That is too few expected variants to judge how well the gene tolerates losing a copy. Missense variants: 142 observed, 155.71 expected, observed/expected ratio (o/e) 0.91, 90% interval 0.8 to 1.05. Synonymous variants: 52 observed, 54.17 expected, observed/expected ratio (o/e) 0.96, 90% interval 0.77 to 1.21.
Homologues: Orthologues: chimpanzee PLSCR2 (99% identical), macaque PLSCR2 (94% identical), zebrafish si:ch211-71m22.5 (60% identical), zebrafish plscr3b (59% identical), zebrafish si:ch211-71m22.1 (58% identical), zebrafish si:ch73-206p6.1 (58% identical), zebrafish plscr3a (54% identical), zebrafish si:dkey-62k3.6 (45% identical), Caenorhabditis elegans scrm-1 (41% identical), Caenorhabditis elegans scrm-2 (41% identical), zebrafish si:ch73-170d6.4 (33% identical), Caenorhabditis elegans scrm-3 (32% identical), and 7 more. Paralogues in human: PLSCR1 (84% identical), PLSCR5 (61% identical), PLSCR3 (54% identical), PLSCR4 (50% identical).
Diseases named in the same sentence as PLSCR2 in open-access papers:
PLSCR2 is named in the same sentence as 6 diseases in open-access papers, as found by Europe PMC text mining. Sharing a sentence is not in itself a finding about the gene and the disease. The quoted sentences say what the papers report.
hepatoma (1 paper, 2018). "PLSCR2 was found to be expressed in different mouse cell lines, including MEFs and ML-1, a hepatoma cell line, although the basal levels of PLSCR2 were lower in MEFs than in ML-1 cells." (PMID 30158934, 2018).
leukemia (1 paper, 2016). A malignant (clonal) hematologic disorder, involving hematopoietic stem cells and characterized by the presence of primitive or atypical myeloid or lymphoid cells in the bone marrow and the blood. "Intriguingly, a recent study showed that anthracyclines are able to trigger type I IFN signalling in murine sarcoma, mammary carcinoma and leukemia cell lines, including the transcription of several Interferon stimulated-genes (ISGs) and also of PLSCR2." (PMID 27248824, 2016).
viral infection (1 paper, 2018). "Nevertheless, the mode of action of TRIM29 is completely different from that of PLSCR2, as the latter does not alter the production of IFN-I during viral infection." (PMID 30158934, 2018).
PLSCR2 also shares sentences with these, for which no sentence is quoted: diabetic nephropathy (1 paper); mammary carcinoma (1); sarcoma (1).